UVSSA (UV stimulated scaffold protein A)
Description:
Factor involved in transcription-coupled nucleotide excision repair (TC-NER), a mechanism that rapidly removes RNA polymerase II-blocking lesions from the transcribed strand of active genes. Acts as a key adapter that promotes recruitment of factors involved in TC-NER. Facilitates the ubiquitination of the elongating form of RNA polymerase II (RNA pol IIo) at DNA damage sites, thereby promoting RNA pol IIo backtracking and access by the TC-NER machinery to lesion sites. Also promotes stabilization of ERCC6/CSB by recruiting deubiquitinating enzyme USP7 to TC-NER complexes, preventing UV-induced degradation of ERCC6 by the proteasome. Mediates the recruitment of the TFIIH complex and other factors that are required for nucleotide excision repair to RNA polymerase II. Also required to inactivate stalled RNA polymerase II by blocking the access of TCEA1/TFIIS, thereby preventing reactivation of RNA polymerase II. Not involved in processing oxidative damage.
Synonyms: KIAA1530; UVSS3
Tractability: Small molecule: a structure with a bound ligand is known. PROTAC: UniProt records ubiquitination sites on it; ubiquitination databases record sites on it.
Gene: Protein-coding gene on chromosome 4 (1,345,691 to 1,395,989, forward strand). Ensembl gene ENSG00000163945.
Subcellular location: Chromosome
Subcellular location (Human Protein Atlas): Nucleoplasm
Pathways (Reactome):
DNA Repair: Dual incision in TC-NER; Formation of TC-NER Pre-Incision Complex; Gap-filling DNA repair synthesis and ligation in TC-NER; Transcription-Coupled Nucleotide Excision Repair (TC-NER)
Gene Ontology:
Molecular function: chromatin-protein adaptor activity; protein binding; RNA polymerase II complex binding; RNA polymerase inhibitor activity
Biological process: protein ubiquitination; response to UV; transcription-coupled nucleotide-excision repair; chromatin organization
Cellular component: chromosome; nucleoplasm; nucleus; site of DNA damage
Genetic constraint (gnomAD): Loss-of-function variants: 73 observed, 73.05 expected, observed/expected ratio (o/e) 1, 90% interval 0.83 to 1.21. The upper end of that interval is the gene's LOEUF score, 1.21, which puts it in group 5 of 6, group 1 being the genes least tolerant of losing a copy. Missense variants: 1,146 observed, 984.13 expected, observed/expected ratio (o/e) 1.16, 90% interval 1.11 to 1.22. Synonymous variants: 454 observed, 403.64 expected, observed/expected ratio (o/e) 1.12, 90% interval 1.04 to 1.22.
Homologues: Orthologues: chimpanzee UVSSA (95% identical), macaque UVSSA (94% identical), mouse Uvssa (72% identical), guinea pig UVSSA (71% identical), rat Uvssa (70% identical), pig UVSSA (67% identical), dog UVSSA (63% identical).
Diseases named in the same sentence as UVSSA in open-access papers:
UVSSA is named in the same sentence as 12 diseases in open-access papers, as found by Europe PMC text mining. Sharing a sentence is not in itself a finding about the gene and the disease. The quoted sentences say what the papers report.
Cockayne syndrome (5 papers, 2021 to 2025). A multisystem condition characterized by short stature, a characteristic facial appearance, premature aging, photosensitivity, progressive neurological dysfunction, and intellectual deficit. "Mutations in CSA and CSB cause severe Cockayne syndrome (CS), which is characterized by premature ageing and progressive neurodegeneration, whereas UVSSA mutations cause the mild UV-sensitive syndrome, with specific cutaneous phenotypes such as freckling and photosensitivity." (PMID 38600236, 2024). "Strikingly, UVSSA deficiency results in UV-Sensitive Syndrome (UVSS), with mild cutaneous symptoms, while loss of CSA or CSB activity results in the severe Cockayne Syndrome (CS), characterized by neurodegeneration and premature aging." (PMID 39021334, 2024). "Unlike the core TC-NER factors CSB, CRL4CSA, and UVSSA, mutations in which give rise to Cockayne syndrome and UV-sensitive syndrome, respectively, STK19 and ELOF1 have not yet been linked to these human disorders." (PMID 39547228, 2024).
UV-sensitive syndrome (4 papers, 2019 to 2024). UV-sensitive syndrome is a condition that is characterized by sensitivity to the ultraviolet (UV) rays in sunlight. "A mutation in the UVSSA gene has been found to be causative for the autosomal recessive disorder UV-sensitive syndrome in humans and together with USP7 it mediates the transcription-coupled nucleotide excision repair." (PMID 31261764, 2019).
xeroderma pigmentosum (2 papers, 2021 to 2024). Xeroderma pigmentosum (XP) is a rare genodermatosis characterized by extreme sensitivity to ultraviolet (UV)-induced changes in the skin and eyes, and multiple skin cancers. "Mutations in genes XPA to XPG can cause xeroderma pigmentosum (XP), whereas mutations in CSA and CSB can cause Cockayne syndrome (CS) or, together with mutations in UVSSA, UV-sensitive syndrome." (PMID 38664429, 2024).
autoimmune disorders (1 paper, 2025). "STK19 was one of several genes found in a genome wide association study (GWAS) in metabolic syndrome and inflammation, and UVSSA is one of 27 genes identified in a natural killer cell transcriptome-wide association study carried out across five autoimmune disorders." (PMID 40894167, 2025).
tumor (3 papers, 2019 to 2022). "A defective transcription-coupled-nucleotide excision repair in the resistant tumour due to mutation of the UVSSA gene may be implicated in the mechanism of resistance." (PMID 31409911, 2019). "The genomic sequence of the UVSSA gene, a component of the transcription-coupled nucleotide excision repair (TC-NER), harboured CNA and a SNV in the ML017/ET tumours only." (PMID 31409911, 2019). "To support the hypothesis that the UVSSA gene is involved in trabectedin resistance, we examined by ddPCR the presence of the SNV and the CNA in tumour biopsies from ML017 mice after different cycles of exposure to trabectedin." (PMID 31409911, 2019).
skin disorder (1 paper, 2019). Any deviation from the normal structure or function of the skin or subcutaneous tissue that is manifested by a characteristic set of symptoms and signs. "Our study revealed very high frequencies (up to 95%) of chestnut horses harboring NFKB1, SLC39A8, BANK1 and UVSSA in ROH islands, and indicated evidence that these genes may be involved in the reported higher susceptibility of chestnut horses for skin disorders." (PMID 31261764, 2019).
UVSSA also shares sentences with these, for which no sentence is quoted: colorectal cancer (1 paper); Fanconi anemia (1); metabolic syndrome (1); Spastic paraplegia (1); trichothiodystrophy (1); Troyer syndrome (1).